DIAPH1 (diaphanous related formin 1)
Diseases named in the same sentence as DIAPH1 in open-access papers (continued):
Sharing a sentence is not in itself a finding about the gene and the disease.
colon carcinoma (5 papers, 2015 to 2022). "DIAPH1 expression is increased in patients with colorectal cancer, and its downregulation strongly reduces the metastatic capacity of colon carcinoma cells." (PMID 36589226, 2022). "Recently, we found a specific up-regulation of Diaph1 in patient samples from colorectal carcinomas and showed a positive correlation between Diaph1 expression and the presence of colon cancer metastasis." (PMID 30926831, 2019). "Recently we have revealed that depletion of DIAPH1 in colon cancer cells (HCT-116 cells) strongly reduced lung metastasis in SCID mice." (PMID 26124177, 2015). "Recently, we found DIAPH1 being specifically up-regulated in patient samples from colorectal carcinomas and found a positive correlation between DIAPH1 expression and the presence of colon cancer metastasis." (PMID 26124177, 2015). "Mechanistically, the strong effect of DIAPH1 depletion on metastasis of colon cancer cells can be explained by our result that DIAPH1 is essential for one of the earliest steps in the metastatic cascade; cellular adhesion to the ECM." (PMID 26124177, 2015). "Recently, we showed strongly reduced lung metastasis of DIAPH1-depleted colon cancer cells but we found accumulations of DIAPH1-depleted cells in bone marrow." (PMID 26124177, 2015). "Recent data revealed that the blockade of DIAPH1-tubulin interaction might be a promising approach to inhibit one of the earliest steps in the metastatic cascade of colon cancer." (PMID 27259239, 2016). "we aimed to determine whether DIAPH1-depleted human colon cancer cells show organ- or tissue-specific metastases besides the lungs." (PMID 26124177, 2015). "Thus, blockade of DIAPH1-tubulin interaction may be a promising approach to inhibit one of the earliest steps in the metastatic cascade of colon cancer." (PMID 26124177, 2015). "In summary our data demonstrate that also in absence of LPA stimulation, DIAPH1 is essential for MT-dependent cellular adhesion of HCT-116 colon cancer cells, thus facilitates one of the first steps in the metastatic cascade." (PMID 26124177, 2015). "We found, indeed, that even under non-stimulating conditions, depletion of DIAPH1 reduced adhesion of HCT-116 colon cancer cells to collagen by 50%." (PMID 26124177, 2015). "Our assumption that DIAPH1 controls adhesion of non-stimulated HCT-116 colon cancer cells by stabilizing MTs had to be proven because up to now the MT-stabilizing effect of DIAPH1 was only shown after preventing its auto-inhibition." (PMID 26124177, 2015). "This insight of its metastasis-promoting activity in colon cancer cells was additionally confirmed by a subcutaneous SCID mouse model, showing that lung metastasis of HCT-116 cells was almost completely blocked after depletion of DIAPH1." (PMID 26124177, 2015). "We aimed to analyze DIAPH1-effects on cellular adhesion and cytoskeletal dynamics in colon cancer cells that were not specifically stimulated with LPA." (PMID 26124177, 2015). "Since the FH2 domain is essential for all known DIAPH1-mediated cellular effects, identification of drugs specifically blocking the interaction of FH2 with tubulin and actin, respectively, may be a promising new therapeutic approach for metastasizing colon cancers." (PMID 26124177, 2015). "However, it leaves future studies to reveal whether this assumption proves true on a molecular level, or whether other factors besides LPA also play a regulative role in DIAPH1-mediated MT-stabilization in non-stimulated colon cancer cells." (PMID 26124177, 2015).
colorectal cancer (5 papers, 2015 to 2022). A primary or metastatic malignant neoplasm that affects the colon or rectum. "Clinical studies have shown that the expression of the DIAPH1 protein is significantly upregulated in tissues of patients with colorectal cancer and laryngeal cancer." (PMID 36589226, 2022). "A colorectal cancer study demonstrated that SCIN knockdown significantly reduced DIAPH1 expression and SCIN served as an independent predictor of poor prognosis, which implies that high DIAPH1 expression may be associated with poor prognosis." (PMID 34631544, 2021).
Insulin resistance (5 papers, 2019 to 2025). Increased resistance towards insulin, that is, diminished effectiveness of insulin in reducing blood glucose levels. "Moreover, because Diaph1 may also affect insulin resistance, and given that our mice had a global deletion of Diaph1, we aimed to determine whether their overall health was impacted in our T1D model." (PMID 41148850, 2025).
Autosomal dominant deafness (4 papers, 2021 to 2024). "Since then, several families with autosomal dominant deafness have been reported to carry mutations in DIAPH1." (PMID 35681420, 2022). "Autosomal dominant deafness caused by mutations in the DIAPH1 gene can be associated with thrombocytopenia." (PMID 34795337, 2021). "We investigated the potential association of DIAPH1 as a novel candidate gene linked to dominant MTP and autosomal dominant non-syndromic hearing loss (ADNSHL), which was evaluated through audiometry." (PMID 38915998, 2024).
glioblastoma (4 papers, 2019 to 2024). The most malignant astrocytic tumor (WHO grade IV). "Conversely, FMNL1 downregulation suppressed glioblastoma multiforme cell migration and invasion via DIAPH1 and GOLGA2, respectively." (PMID 31861134, 2019). "DIAPH1 knockdown promotes apoptosis in human glioblastoma cells." (PMID 38401037, 2024).
Hyperglycemia (4 papers, 2022 to 2025). An increased concentration of glucose in the blood. "Overall, our data presented here indicates that RAGE/Diaph1 signaling is likely to play a role in altering actin dynamics in nerve fibers in response to hyperglycemia." (PMID 41303665, 2025). "We found that hyperglycemia reduces both the axon and the g ratio in WT mice, but deleting Diaph1 and AGER together prevents this reduction to a similar extent." (PMID 41303665, 2025). "Based on our previous work and the literature, we hypothesized that aberrant RAGE/Diaph1 signaling in hyperglycemia likely alters molecules involved in actin polymerization, thus impacting axonal structure." (PMID 41303665, 2025). "Within the sciatic nerve (SCN), the lack of Diaph1 failed to prevent hyperglycemia-induced loss of β-actin in the nerve fibers." (PMID 41148850, 2025). "Experimental evidence suggests that in chronic hyperglycemia, formation of RAGE/Diaph1 molecular complex in peripheral nerves leads to an aberrant actin cytoskeletal dynamic which contributes to DPN progression." (PMID 41303665, 2025). "Similar to WT mice, they also rapidly lose weight upon induction of hyperglycemia, indicating that not all adverse metabolic effects of hyperglycemia can be negated by abolishing RAGE/Diaph1 signaling." (PMID 41303665, 2025). "We demonstrate that simultaneous deletion of Diaph1 and RAGE did not change the course or the intensity of hyperglycemia-induced weight loss in mice." (PMID 41303665, 2025). "Put together, our data indicates that DRKO mice were almost completely devoid of negative signs of hyperglycemia, hence we examined the effect of Diaph1 and AGER deletion on the functionality of the sciatic nerve fibers." (PMID 41303665, 2025). "Furthermore, the lack of Diaph1 failed to rescue motor or sensory nerve conduction defects resulting from hyperglycemia over 6 months." (PMID 41148850, 2025).
diabetic kidney disease (3 papers, 2022 to 2023). Progressive kidney disorder caused by vascular damage to the glomerular capillaries, in patients with diabetes mellitus. "In addition, DIAPH1-deficient diabetic mice also exhibited a protective effect on diabetic kidneys compared to diabetic mice expressing DIAPH1, suggesting that DIAPH1 is involved in the pathophysiological processes of diabetic nephropathy." (PMID 35967420, 2022). "In addition, experiments in mice globally devoid of Diaph1 illustrated protective benefits in models of arterial injury, cardiac ischemia/reperfusion injury and diabetic kidney disease (DKD)." (PMID 35562970, 2022).
Intellectual disability (3 papers, 2021 to 2025). "Mutations of other formin genes in addition to DIAPH1 and FMN2 have been associated with intellectual disability." (PMID 34685534, 2021). "Mutations of DIAPH1, FMN2, and INF2 are associated, to varying degrees, with intellectual disability and neurodevelopmental disorders." (PMID 34685534, 2021).
ischemic stroke (3 papers, 2020 to 2025). A stroke disorder caused by obstruction of blood flow to the brain, due to thrombotic (local blood clot formation) or embolic (due to a blood clot or other material traveling from another site) event. "An intronic variant in DIAPH1 was associated with increased risk of ischemic stroke and some DIAPH1 variants have also been associated with Moyamoya disease, which is a progressive vasculopathy that causes stroke in children." (PMID 34685534, 2021). "The possible role of altered DIAPH1 in ischemic stroke could be related to the involvement of RAGE/DIAPH1 in neuroinflammation and neurodegenerative diseases." (PMID 34685534, 2021).
laryngeal squamous cell carcinoma (3 papers, 2019 to 2024). A squamous cell carcinoma that arises from the larynx. "Here, through bioinformatics analysis, we found that high expression of diaphanous related formin 1 (DIAPH1) was associated with poor overall survival in head and neck squamous cell carcinoma and laryngeal squamous cell carcinoma (LSCC)." (PMID 30733838, 2019). "RNA-sequencing analysis of AMC-HN-8 NC and SH1 cells also cannot be provided because further research based on the analysis is being carried out to verify the role of DIAPH1 in laryngeal squamous cell carcinoma." (PMID 30733838, 2019). "DIAPH1 is upregulated in laryngeal squamous cell carcinoma and may inhibit apoptosis in LSCC cells." (PMID 38401037, 2024). "In the current study, we have revealed that DIAPH1 expression is an independent prognostic factor for overall survival in patients with laryngeal squamous cell carcinoma (LSCC) and that DIAPH1 promotes colony formation, cell proliferation, and G1/S progression in LSCC cells." (PMID 34631544, 2021).
Moyamoya disease (3 papers, 2021 to 2023). Moyamoya disease (MMD) is a rare intracranial arteriopathy involving progressive stenosis of the cerebral vasculature located at the base of the brain causing transient ischemic attacks or strokes. "We have identified a different Asian Moyamoya disease and European DIAPH1 mutation with a site associated with posterior circulation involvement." (PMID 37400591, 2023). "DIAPH1 gene mutation is not a major genetic risk gene for Asian patients with moyamoya disease but may play an important role in the involvement of posterior cerebral artery." (PMID 37400591, 2023).
neuropathy (3 papers, 2013 to 2025). A disorder affecting the nervous system that manifests with pain, tingling, numbness, and/or muscle weakness. "Studies have shown that blocking Diaph1 interaction with RAGE reduces the progression of neuropathy." (PMID 41303665, 2025). "Binding of a receptor for advanced glycosylation end products (RAGE) with cell surface receptors and its cytoplasmic structural domain interacts with Diaphanous Related Formin 1(DIAPH1) on the cytoskeleton, whose dysfunction may lead to neuropathy." (PMID 37056668, 2023).
ovarian carcinoma (3 papers, 2014 to 2022). A malignant neoplasm originating from the surface ovarian epithelium. "For ovarian cancer patients, high DIAPH1 expression was associated with low differentiated tumors, while high DIAPH1 expression was associated with increased OS." (PMID 34631544, 2021). "High DIAPH1 protein levels are associated with poor prognosis in ovarian cancer patients." (PMID 36589226, 2022). "suspected that an increased response to chemotherapeutics caused by high DIAPH1 levels may explain why elevated DIAPH1 expression was associated with increased OS in ovarian cancer patients." (PMID 34631544, 2021).
Stroke (3 papers, 2020 to 2021). Sudden impairment of blood flow to a part of the brain due to occlusion or rupture of an artery to the brain. "To this end, we performed case-control and cohort studies to evaluate the association of single-nucleotide polymorphisms (SNPs) in the human DIAPH1 gene with susceptibility to hypertension and stroke." (PMID 31899686, 2020). "In conclusion, the current study reports original evidence for the association of genetic variation in the DIAPH1 gene with stroke risk, especially the SAO subtype of IS." (PMID 31899686, 2020). "The present findings provide novel insights about the potential contribution of DIAPH1 polymorphisms to the pathogenesis of hypertension and stroke." (PMID 31899686, 2020). "These novel findings suggest that DIAPH1 variation contributes to genetic susceptibility to stroke risk, especially the SAO subtype of IS." (PMID 31899686, 2020). "The current study conducted case-control and cohort studies to investigate the associations of DIAPH1 polymorphisms with hypertension and stroke." (PMID 31899686, 2020). "On account of the important role of DIAPH1 on vascular remodeling and thrombosis, i.e. two key aspects in the pathophysiology of stroke, we decided to investigate potential associations between DIAPH1 gene variations and stroke risk." (PMID 31899686, 2020). "Association analyses of DIAPH1 SNPs with stroke sub-types in the case-control study." (PMID 31899686, 2020). "First, by selecting candidate SNPs with the criterion MAF ≥ 0.05 we may have missed the chance of evaluating rare variants in DIAPH1 also associated to stroke or hypertension." (PMID 31899686, 2020). "The novel associations detected between DIAPH1 rs7703688 and stroke may provide further insight about molecular differences between etiological stroke subtypes, especially in the Asian population." (PMID 31899686, 2020). "Association analyses of DIAPH1 SNPs and hypertension and stroke in the cohort study." (PMID 31899686, 2020). "First, the positive DIAPH1 loci associated with stroke could be mutually validated by the case-control and cohort study design." (PMID 31899686, 2020). "In SAO stroke subtype, DIAPH1 expression has an increased trend among rs251019 genotypes (Ptrend=0.048)." (PMID 31899686, 2020). "Further work to elucidate the specific influence of DIAPH1 gene variation on cerebrovascular conditions may help discover new pharmacological targets and design better therapies against stroke." (PMID 31899686, 2020). "Whether DIAPH1 polymorphisms affect stroke susceptibility had not been so far determined in GWAS." (PMID 31899686, 2020). "However, whether changes in DIAPH1 expression or function may contribute to stroke incidence has not been established." (PMID 31899686, 2020).
B cell lymphoma (2 papers, 2021 to 2025). "Interestingly, three affected individuals with SCBMS developed B cell lymphoma suggesting that, in a manner similar to loss of WASP, mutations in DIAPH1 may also increase the risk of developing lymphoid tumours." (PMID 40368919, 2025).
inflammatory bowel disease (2 papers, 2019 to 2024). A spectrum of small and large bowel inflammatory diseases of unknown etiology. "Here we present DIAPH1 deficiency as an unexpected genetic finding in a child with fatal inflammatory bowel disease who also displayed complex neurological and developmental phenotypes." (PMID 39076976, 2024). "DIAPH1 dysregulation within the actin-cytoskeleton pathway may specifically promotes malignant transformation in inflammatory bowel disease-associated CRC." (PMID 31736743, 2019).
ischemia (2 papers, 2023). A hypoperfusion of the BLOOD through an organ or tissue caused by a PATHOLOGIC CONSTRICTION or obstruction of its BLOOD VESSELS, or an absence of BLOOD CIRCULATION. "Introduction of synthetic linker construct, which shorten the mitochondria-SR/ER distance, mitigated the molecular and functional benefits of DIAPH1 silencing in ischemia." (PMID 37903764, 2023).
polycystic ovary syndrome (2 papers, 2022 to 2024). A disorder that manifests as multiple cysts on the ovaries. "In addition, the plasma DIAPH1 levels were found to be associated with sex hormones (estrogen, progesterone, and luteinizing hormone (LH)/follicle-stimulating hormone (FSH) in patients with polycystic ovary syndrome." (PMID 39010074, 2024). "We investigated whether plasma DIAPH1 levels were a potential prognostic predictor for polycystic ovary syndrome (PCOS)." (PMID 35185386, 2022).
sensorineural hearing loss (2 papers, 2021 to 2025). "Almost 25 years have passed since a mutation of a formin gene, DIAPH1, was identified as being responsible for a human inherited disorder: a form of sensorineural hearing loss." (PMID 34685534, 2021). "Increased gene dosage of DIAPH1 has been documented in several cases of sporadic sensorineural hearing loss in humans." (PMID 34685534, 2021).
aspergillosis (1 paper, 2022). Aspergillosis is an infection, growth, or allergic response caused by the Aspergillus fungus. "In his study, we present the characteristics of an Iranian boy with SCBMS and CD4 deficiency, reporting the first case of aspergillosis associated with the NM_005219.5 c.3145C > T; p.R1049X variant of homozygous DIAPH1 loss." (PMID 36212620, 2022). "Similarly, our patient also had recurrent pulmonary infections and a CMV urinary tract infection, though he also developed COVID-19 and aspergillosis, which were yet to be reported in patients with homozygous DIAPH1 loss." (PMID 36212620, 2022). "Furthermore, aspergillosis isyet to be reported in patients with homozygous DIAPH1 loss." (PMID 36212620, 2022).
bronchiectasis (1 paper, 2024). Segmental, irreversible dilation of the bronchial tree resulting in the accumulation of secretions which leads to obstruction. "Although infectious or immunological phenotypes were not highlighted in this initial report of DIAPH1 deficiency, one of the patients died at age 18 of a chest infection (causal pathogen not reported), and another patient had a history of bronchiectasis." (PMID 39076976, 2024).
ciliopathies (1 paper, 2021). "Since mutations in DIAPH1-3 gave clinical phenotypes similar to known ciliopathies, we have investigated whether DIAPH proteins contribute to ciliogenesis." (PMID 33872598, 2021).
colorectal tumor (1 paper, 2022). "As examples, the LEF1-AS1 expression could be induced by CREB1, and the high expression of LEF1-AS1 promoted tumorigenesis of colorectal tumor through sponging miR-489 and stabilizing DIAPH1." (PMID 35371339, 2022).
DNA repair deficiency disorders (1 paper, 2025). "Consistent with this, we have identified a cohort of >30 patients with biallelic loss-of-function mutations in the actin nucleation factor, DIAPH1, that exhibit a striking clinical similarity to the DNA repair disorders, NBS and WABS24–26." (PMID 40368919, 2025).
endolymphatic hydrops (1 paper, 2008). An accumulation of endolymph in the inner ear (labyrinth) leading to buildup of pressure and distortion of intralabyrinthine structures, such as cochlea and semicircular canals. "An 8-year-old boy with LFSNHL and a DIAPH1 mutation was evaluated with EcochG and found to have an elevated SP/AP ratio, suggestive of endolymphatic hydrops." (PMID 18518985, 2008).
Glucose intolerance (1 paper, 2022). Glucose intolerance (GI) can be defined as dysglycemia that comprises both prediabetes and diabetes. "This discordance suggests that glucose intolerance and insulin secretion disorder play an integrated role in DIAPH1 levels." (PMID 35185386, 2022).
head and neck squamous cell carcinoma (1 paper, 2019). A squamous cell carcinoma that arises from any of the following anatomic sites: lip and oral cavity, nasal cavity, paranasal sinuses, pharynx, larynx, and salivary glands. "Further experiments verify that DIAPH1 is involved in the wound healing and the metastasis of head and neck squamous cell carcinoma (HNSCC)." (PMID 30733838, 2019).